AKAP6 (A-kinase anchoring protein 6)
Description:
Binds to type II regulatory subunits of protein kinase A and anchors/targets them to the nuclear membrane or sarcoplasmic reticulum. May act as an adapter for assembling multiprotein complexes.
Synonyms: PRKA6; AKAP100; KIAA0311; mAKAP; ADAP6; ADAP100
Tractability: PROTAC: ubiquitination databases record sites on it.
Gene: Protein-coding gene on chromosome 14 (32,329,298 to 32,837,684, forward strand). Ensembl gene ENSG00000151320.
Subcellular location: Sarcoplasmic reticulum; Nucleus membrane
Gene Ontology:
Molecular function: protein binding; transmembrane transporter binding; adenylate cyclase binding; cytoskeleton-nuclear membrane anchor activity; molecular adaptor activity; protein kinase A binding; protein kinase A regulatory subunit binding; protein-membrane adaptor activity
Biological process: action potential; cellular response to cAMP; positive regulation of potassium ion transmembrane transport; regulation of membrane repolarization; adenylate cyclase-activating G protein-coupled receptor signaling pathway; cAMP/PKA signal transduction; cellular response to cytokine stimulus; positive regulation of calcineurin-NFAT signaling cascade; positive regulation of cell growth; positive regulation of cell growth involved in cardiac muscle cell development; positive regulation of release of sequestered calcium ion into cytosol; protein targeting; regulation of cAMP/PKA signal transduction; regulation of relaxation of cardiac muscle; regulation of release of sequestered calcium ion into cytosol by sarcoplasmic reticulum; positive regulation of cation transmembrane transport; regulation of metal ion transport
Cellular component: calcium channel complex; nuclear envelope; perinuclear region of cytoplasm; sarcoplasmic reticulum; caveola; cytoplasm; intercalated disc; junctional sarcoplasmic reticulum membrane; nuclear membrane; T-tubule; membrane; protein-containing complex
Genetic constraint (gnomAD): Loss-of-function variants: 56 observed, 190.52 expected, observed/expected ratio (o/e) 0.29, 90% interval 0.24 to 0.37. The upper end of that interval is the gene's LOEUF score, 0.37, which puts it in group 1 of 6, group 1 being the genes least tolerant of losing a copy. Missense variants: 2,690 observed, 2,855.5 expected, observed/expected ratio (o/e) 0.94, 90% interval 0.91 to 0.97. Synonymous variants: 979 observed, 1,049.2 expected, observed/expected ratio (o/e) 0.93, 90% interval 0.88 to 0.98.
Homologues: Orthologues: chimpanzee AKAP6 (99% identical), macaque AKAP6 (97% identical), dog AKAP6 (88% identical), pig AKAP6 (88% identical), rabbit AKAP6 (87% identical), guinea pig AKAP6 (81% identical), mouse Akap6 (81% identical), rat Akap6 (80% identical), zebrafish akap6 (40% identical), tropical clawed frog akap6 (36% identical). Paralogues in human: CEP68 (5% identical).
Diseases named in the same sentence as AKAP6 in open-access papers:
AKAP6 is named in the same sentence as 29 diseases in open-access papers, as found by Europe PMC text mining. Sharing a sentence is not in itself a finding about the gene and the disease. The quoted sentences say what the papers report.
cardiac hypertrophy (6 papers, 2014 to 2023). "We searched the literature and discovered that among the dozens of genes filtered out, Akap6 is a well-studied gene in cardiomyocytes encoding the protein that participates in cardiac hypertrophy process." (PMID 36105283, 2022). "AKAP6 can regulate cardiac hypertrophy pathways by anchorage of cAMP-dependent protein kinase A (PKA), providing spatial and temporal control of cAMP signalling and PKA phosphorylation." (PMID 37171063, 2023). "In brief, the modulation of multiple cardiac hypertrophy and failure signaling pathways was mediated by AKAP6 scaffold protein." (PMID 36105283, 2022). "The binding of CaNAβwith AKAP6 influences Ca2+ release in myocytes and is required for the formation of pathological cardiac hypertrophy." (PMID 36105283, 2022). "AKAP6 is a well-known master scaffold protein that orchestrates cardiac hypertrophy and heart failure signaling." (PMID 36105283, 2022). "Further assays showed that BACH2 bound to the promotor region of Akap6 at the -600 to -587 site and repressed its expression, which functioned as a crucial scaffold for cardiac hypertrophy and failure signaling pathways." (PMID 36105283, 2022). "AKAP6 integrates multiple signaling pathways involved in the induction and formation of cardiac hypertrophy and failure which is induced by diverse malignant stimuli including cytokines, growth factors and pressure overload." (PMID 36105283, 2022). "Among the screened genes, Akap6 is well known for its role in cardiac hypertrophy and failure process." (PMID 36105283, 2022). "Additionally, the association of nesprin-1α2 and AKAP6 was shown to be necessary for the NE localisation of RyR and AKAP6-mediated cardiac hypertrophy in rat hearts occurred via RyR2 phosphorylation." (PMID 37171063, 2023). "Moreover, it has been demonstrated that cardiomyocyte-specific knockout of Akap6 in mice or knockdown of Akap6 by siRNA in cardiomyocytes has protective effects against corresponding TAC-induced cardiac hypertrophy and heart failure or ISO-triggered cardiomyocyte hypertrophy." (PMID 36105283, 2022). "Nesprin-1α2, AKAP6, and AKAP9 were shown to form a protein platform tethering the Golgi to the nucleus, that is required for proper induction of downstream cardiac hypertrophy cascades, suggesting cell-specific functions of perinuclear MTs." (PMID 37171063, 2023).
heart failure (4 papers, 2020 to 2023). Inability of the heart to pump blood at an adequate rate to meet tissue metabolic requirements. "Moreover, it has been shown that genetic deletion of AKAP6 prevents the development of heart failure associated with long-term transverse aortic constriction, conferring a survival benefit." (PMID 33295871, 2020). "This contrasts with what has been shown for other AKAPs expressed in the heart, including AKAP6 and phosphatidyl inositol 3 kinase γ (PI3Kγ), whose upregulation in response to stress leads to cardiac remodeling and heart failure." (PMID 34831084, 2021).
Anorexia (3 papers, 2013 to 2018). Lack of desire to eat (loss of appetite). "One of the genes in anorexia, namely AKAP6, is also associated to fasting insulin-related traits as well as the autoimmune disease Ankylosing spondylitis." (PMID 23936387, 2013).
glioma (3 papers, 2019 to 2022). A benign or malignant brain and spinal cord tumor that arises from glial cells (astrocytes, oligodendrocytes, ependymal cells). "Polymorphisms in AKAP6 have been acknowledged to increase the risk of developing glioma in patients, including high-grade glioma in Han Chinese adults." (PMID 34065872, 2021). "We found that AKAP6 single nucleotide polymorphisms rs2239647 and rs2145587 were associated with glioma susceptibility." (PMID 31759389, 2019). "Our aim was to clarify the correlation between Kinase-anchored protein 6 (AKAP6) gene polymorphisms and glioma susceptibility and prognosis in Chinese Han population." (PMID 31759389, 2019). "In summary, our results show that AKAP6 polymorphism is associated with the susceptibility and prognosis of glioma in the Chinese Han population." (PMID 31759389, 2019). "In this case-control study, we investigated the correlation between AKAP6 single nucleotide polymorphisms and glioma susceptibility and prognosis in the Han Chinese population." (PMID 31759389, 2019). "This study confirmed the relationship between AKAP6 gene variation and glioma risk or prognosis in Han Chinese population." (PMID 31759389, 2019). "In this study, it was found that the SNPs of AKAP6 were significantly correlated with the susceptibility and prognosis of glioma." (PMID 31759389, 2019). "Five single-nucleotide polymorphisms (SNPs) of AKAP6 were genotyped by Agena MassARRAY in 575 glioma patients and 500 healthy controls." (PMID 31759389, 2019). "Based on previous results, we hypothesized that AKAP6 gene polymorphisms may be related to the pathogenesis of glioma." (PMID 31759389, 2019). "This study firstly provided evidence for the impact of AKAP6 polymorphisms on susceptibility and prognosis of glioma, suggesting AKAP6 variants might have potential roles in the etiology of glioma." (PMID 31759389, 2019). "We found that AKAP6-rs2239647 significantly affected the PFS of patients with high-level glioma (WHO grade III–IV), and patients with CA genotype had a better prognosis (PFS: log-rank p = 0.045, HR = 1.67, p = 0.034)." (PMID 31759389, 2019). "This indicates that AKAP6 gene plays an important role in the occurrence and development of glioma." (PMID 31759389, 2019). "We will verify the function of AKAP6 gene in glioma through experiments in subsequent studies." (PMID 31759389, 2019). "However, no literature supports the effect of AKAP6 polymorphisms on glioma." (PMID 31759389, 2019).
Alzheimer disease (2 papers, 2016 to 2019). A progressive, neurodegenerative disease characterized by loss of function and death of nerve cells in several areas of the brain leading to loss of cognitive function such as memory and language. "Genome-wide association studies (GWAS) have confirmed that the SNPs of AKAP6 were associated with brain-related diseases, such as Alzheimer’s disease, anorexia nervosa, and poor cognitive, better memory abilities." (PMID 31759389, 2019). "AKAP6-rs4296166 has been associated with risk of Alzheimer’s disease, and rs2383378 was suggestively associated with anorexia nervosa." (PMID 31759389, 2019).
anorexia nervosa (2 papers, 2016 to 2019). A disorder most often seen in adolescent females characterized by a refusal to maintain a minimally normal body weight, an intense fear of gaining weight, a disturbance in body image, and, in postmenarcheal females, the development of amenorrhea. "Of those nine genes, AKAP6 and NTNG1 were genes associated with anorexia nervosa and the remaining seven (AGT, CD36, CD38, FOXP1, PPARA, PPARG and SELL) were selected for their relationship with T2D." (PMID 27483138, 2016). "A total of eleven of genes were differently expressed in celiac patients compared with disease controls of which CD36, CD38, FOXP1, SELL, PPARA, PPARG, AGT previously associated with type 2 diabetes and AKAP6, NTNG1 with anorexia nervosa remained significant after correction for multiple testing." (PMID 27483138, 2016). "AKAP6 and NTNG1 were previously reported in a GWAS of anorexia nervosa." (PMID 27483138, 2016).
schizophrenia (2 papers, 2022 to 2023). A major psychotic disorder characterized by abnormalities in the perception or expression of reality. "We also found genetic variants in other two loci encompassing AKAP6 and SEMA6D genes, previously associated with increased risk of schizophrenia, lower cognitive ability and educational attainment, all of them related with shorter life expectancy." (PMID 36906694, 2023).
astroglioma (1 paper, 2019). "Subsequently, we analyzed the effect of AKAP6 polymorphisms on the prognosis of patients with astroglioma." (PMID 31759389, 2019).
dementia (1 paper, 2017). Loss of intellectual abilities interfering with an individual's social and occupational functions. "Two of these genes were independently mutated in more than one family with similar phenotypes, which substantiates their link to human disease (AKAP6 in intellectual disability and UBR4 in early dementia)." (PMID 28600779, 2017). "Although the phenotype associated with AKAP6 is nonspecific developmental delay and seizures, the phenotype we observe in the two families with different heterozygous variants in UBR4 is highly specific and consists of early onset dementia." (PMID 28600779, 2017).
desminopathies (1 paper, 2020). "Thus, targeting AKAP6 to disrupt MTOC at the nuclear envelope might be beneficial to reduce nuclear involution and decrease DNA damage in desminopathies." (PMID 33295871, 2020).
gallbladder tumour (1 paper, 2022).
Insulin resistance (1 paper, 2013). Increased resistance towards insulin, that is, diminished effectiveness of insulin in reducing blood glucose levels. "e.g. genome-wide study of the genetic basis of insulin resistance reported that a variant of AKAP6 was associated with BMI-adjusted fasting insulin (5×10-7) in a meta-analysis cohort of European descent." (PMID 23628382, 2013). "Variants of genes AKAP6, NPAS3, MARCH6 and FBXL7 have been previously reported to be associated with insulin resistance, inflammatory markers or adiposity studies using genome-wide approaches whereas associations of CDH18 and MYO10 with MetS traits have not been reported before." (PMID 23628382, 2013).
Intellectual disability (1 paper, 2017). "AKAP6 was mutated in a patient with intellectual disability (16W-0212)." (PMID 28600779, 2017).
lentivirus infection (1 paper, 2015). Virus diseases caused by the Lentivirus genus. "Successful lentivirus infection was observed as GFP green fluorescence, and AKAP6 knockdown by the shAKAP6-GFP lentivirus was confirmed with western blotting." (PMID 26563778, 2015).
low grade glioma (1 paper, 2019). A grade I or grade II glioma arising from the central nervous system. "At the same time, using GEPIA database analysis, we also found that AKAP6 gene also had a significant impact on the overall survival rate of low-grade glioma patients (p < 0.05)." (PMID 31759389, 2019).
tumor (5 papers, 2017 to 2025). "The significant upregulation of MX2 in high-risk patients, along with the reduced expression of FAM50B, FUCA1, AKAP6, and FCER1A in this group, further supports their potential roles in tumour progression and immune regulation." (PMID 40329678, 2025).
cancer (3 papers, 2010 to 2022). A tumor composed of atypical neoplastic, often pleomorphic cells that invade other tissues. "SNPs of the gene encoding AKAP6, an anchor protein for AMPK, which may connect MetS with cancer, were associated with HC, RQ and REE/leanmass." (PMID 23628382, 2013).
AKAP6 also shares sentences with these, for which no sentence is quoted: gastric cancer (2 papers); Type 2 Diabetes (2); ankylosing spondylitis (1); autoimmune disease (1); breast carcinoma (1); developmental delay (1); dilated cardiomyopathy (1); heart diseases (1); Obesity (1); prostate carcinoma (1); Sepsis (1); thyroid cancer (1).